EGFR (epidermal growth factor receptor)
Diseases named in the same sentence as EGFR in open-access papers (continued):
Sharing a sentence is not in itself a finding about the gene and the disease.
lung adenocarcinoma (continued). "EGFR-mutated lung adenocarcinomas and ErbB2-positive breast and other cancers (such as gastric and lung) are critically dependent on the constitutive activity of these pathways and therapeutic targeting leads to significant clinical benefits." (PMID 29861842, 2018). "Immunohistochemical analysis of Nrf2 and Keap1 in tumor specimens was performed in a total of 104 lung adenocarcinoma patients with the status of EGFR gene mutations or EGFR wide-type." (PMID 29587953, 2018). "We examined surgically resected cases of EGFR-mutated (52 cases) and wild-type (103 cases) lung adenocarcinoma, and identified the unique miRNA–mRNA regulatory network present in EGFR-mutated tumors." (PMID 30404194, 2018). "Epidermal growth factor receptor tyrosine kinase inhibitors (EGFR-TKIs) have become the standard first-line treatment for advanced lung adenocarcinoma (LUAD) cancer patients with activating EGFR mutations." (PMID 30382076, 2018). "In 2958 patients with lung adenocarcinoma having their specimens tested for EGFR mutation, a total of 67 patients with lung adenocarcinoma harboring uncommon EGFR gene mutations, who had received an EGFR TKI treatment, were enrolled." (PMID 30428509, 2018). "EGFR-mutated lung adenocarcinoma, which is responsive to EGFR inhibitors, is characterized by a distinct oncogenic pathway in which unique microRNA (miRNA)–mRNA interactions have been observed." (PMID 30404194, 2018). "In this study, we sought to establish a novel scoring system to predict EGFR subtype mutation in lung adenocarcinomas in a Chinese cohort of patients by using multiple clinical and radiomic features." (PMID 30235778, 2018). "We evaluated the mRNA expression levels of genes encoding MMPs in EGFR-TKI–resistant (PC9/GR and PC9/ER) and EGFR-TKI–sensitive (PC9/6m) lung adenocarcinoma cells using microarray analysis." (PMID 29463039, 2018). "Afatinib has reported good results in some cases of LM in stage IV exon 19-del-EGFR-mutant lung adenocarcinoma in association with WBRT, resulting in an almost complete regression of neurological symptoms as well as good, durable radiological responses." (PMID 29881714, 2018). "Totally fifty-eight patients with stage IV EGFR-mutated lung adenocarcinoma were enrolled into this study." (PMID 29484139, 2018). "We analyzed 422 patients with EGFR-mutated advanced lung adenocarcinoma receiving first-line gefitinib (n = 195, 46.2%), erlotinib (n = 123, 29.1%), or afatinib (n = 104, 24.6%)." (PMID 29849936, 2018). "Pathologically, EGFR-mutated lung adenocarcinoma typically shows nuclear TTF-1 immunoreactivity and hobnail cell morphology." (PMID 29538329, 2018). "The Hippo pathway is a kinase cascade stimulated by the YAP1 oncogene, the activation of which is associated with resistance to EGFR inhibitors in EGFR-mutated lung adenocarcinoma." (PMID 30404194, 2018). "Results of those studies revealed that epithelial-mesenchymal transition, EGF pathway activation, and MET amplification are all significantly associated with increased invasion and migration in lung adenocarcinoma cells resistant to EGFR-TKI." (PMID 29463039, 2018). "The lung adenocarcinoma dataset SRA ERP001058 contains 41 tumors with known targetable or oncogenic mutations in 6 genes: EGFR, KRAS, NRAS, MET, BRAF and CTNNB1." (PMID 30255803, 2018). "A total of 282 patients were screened, and 259 met the inclusion criteria of advanced EGFR mutation-positive lung adenocarcinoma with afatinib as a first-line treatment." (PMID 29805772, 2018). "Brain metastases at the time of the diagnostic stage and the initial treatment response to afatinib are two important prognostic factors for the overall survival of first-line afatinib treated EGFR mutation-positive lung adenocarcinoma." (PMID 29805772, 2018).
lung adenocarcinoma (continued). "On the other hand, exon-20 insertions account for ~5% of all EGFR mutations and define a distinct subset of lung adenocarcinoma characterized by a poor response to the first-generation EGFR-TKIs gefitinib and erlotinib." (PMID 29765525, 2018). "Our study found that CSD is an important independent negative predictive and prognostic factor to EGFR-TKI treatment outcome in patients with EGFR-mutated lung adenocarcinoma." (PMID 30055587, 2018). "The findings supported that Twist expression was linked to EGFR mutations by collaborating with the EGF pathway in promoting EMT in EGFR mutated lung adenocarcinoma." (PMID 29581870, 2018). "A total of 142 patients with advanced or recurrent lung adenocarcinoma with susceptible EGFR mutation treated at Konkuk University Medical Center, Seoul, Korea were retrospectively reviewed between January 2006 and November 2016." (PMID 30055587, 2018). "Mutations in KRAS (Kirsten ras sarcoma viral homolog) and EGFR (epidermal growth factor receptor) are the two most common genetic events in lung adenocarcinoma and account for 30% and 15% of cases respectively." (PMID 29455675, 2018). "In European lung adenocarcinoma patients, the incidence of mutations of epidermal growth factor receptor (EGFR) gene is between 5 to 10%." (PMID 29801465, 2018). "EGFR mutations were first described in lung adenocarcinomas in 2004 and were rapidly recognised as a predictor for response to EGFR tyrosine kinase inhibitors (TKIs)." (PMID 30065223, 2018). "Different EGFR mutations are distinctly expressed in lung adenocarcinoma cells in which EGFR TKIs frequently occur." (PMID 30223434, 2018). "A further large-scale study is necessary to validate our findings, as well as to determine the best treatment modality for patients with lung adenocarcinoma harboring uncommon EGFR mutation." (PMID 30428509, 2018). "The EGFR mutation is one of the most common driver mutations in lung adenocarcinoma, and EGFR-mutated adenocarcinoma is characterized by East Asian ethnicity, female gender, and non-/light-smoking history." (PMID 29538329, 2018). "Lung adenocarcinoma patients with activating mutation of epidermal growth factor receptor (EGFR) had remarkable response to EGFR tyrosine kinase inhibitors (EGFR-TKIs) and better prognosis." (PMID 29484139, 2018). "We examined 155 surgically resected specimens of lung adenocarcinoma with a known EGFR mutation status (52 mutated and 103 wild-type cases)." (PMID 30404194, 2018). "This study retrospectively graded differentially located EGFR expressions in 161 lung adenocarcinoma specimens by using immunohistochemistry (IHC) and determined the association with demographic characteristics, stages, EGFR mutation status, and survival time." (PMID 29950164, 2018). "In this study, we examined 155 surgically resected specimens of lung adenocarcinoma with a known EGFR mutation status (52 mutated and 103 wild-type cases) to identify the complex miRNA–mRNA regulatory network involved in this type of tumor." (PMID 30404194, 2018). "This review summarizes the state of knowledge of tumorigenesis and progression of early lung adenocarcinoma, with a special focus on its clinicopathological characteristics and their associations with driver mutations (EGFR, KRAS, and BRAF)." (PMID 29690599, 2018). "A total of 67 patients with lung adenocarcinoma harboring uncommon EGFR mutations were enrolled and 57 patients with stage IV diseases receiving a first-line EGFR TKI were included for further analyses." (PMID 30428509, 2018). "For Asian patients with exon 19 EGFR-mutant lung adenocarcinoma and brain metastases, erlotinib was associated with a significantly longer OS and a more prolonged PFS and compared with gefitinib." (PMID 30458751, 2018). "Using microarray and bioinformatics analyses, this study is the first comprehensive report of the miRNA–mRNA network present in EGFR-mutated lung adenocarcinoma." (PMID 30404194, 2018).
lung adenocarcinoma (continued). "The left and right lower lobe lung adenocarcinomas contained EGFR gene mutations: an L858R point mutation in exon 21 in the left lesion and a deletion mutation in exon 19 in the right lesion." (PMID 30453894, 2018). "Of note, five of these miRNAs were included in the previously reported 17-miRNA signature in EGFR-mutated lung adenocarcinoma: miR-532-3p, miR-500a-3p, miR-224-5p, miR-502-3p, and miR-532-5p." (PMID 30404194, 2018). "Based on lung adenocarcinoma patients with EGFR mutations responsible to EGFR TKIs, we compared the combined effects of tEGFR protein and EGFR mutations on clinical benefits." (PMID 29950164, 2018). "The Nrf2 positive rate significantly correlated with the status of EGFR gene mutation in lung adenocarcinoma." (PMID 29587953, 2018). "We previously reported that in EGFR mutation-positive putative lung adenocarcinoma presenting as CUP, high PD-L1 positivity (TPS: 80%) was detected." (PMID 30443294, 2018). "In this study, we attempt to assess the association of radiomics features with EGFR exon 19 and 21 mutations of lung adenocarcinomas, respectively." (PMID 30547844, 2018). "Epidermal growth factor receptor-tyrosine kinase inhibitor (EGFR-TKI) treatment has become a standard therapy for patients with advanced lung adenocarcinoma harboring activating EGFR mutations." (PMID 30055587, 2018). "Our findings, if validated, would inform future research examining the interplay of miRNAs and mRNAs in EGFR-mutated lung adenocarcinoma." (PMID 30404194, 2018). "The high expression of Keap1 was not significantly correlated with gender, age, smoking, differentiation, subtype of lung adenocarcinoma and status of EGFR gene mutation (P > 0.05)." (PMID 29587953, 2018). "Epidermal growth factor receptor (EGFR) mutation is a main contributing factor of lung adenocarcinoma (LUAD) in east Asian countries (about 60% of lung adenocarcinoma)." (PMID 30400936, 2018). "With regard to EGFR status, lung adenocarcinomas carrying EGFR mutations have a higher risk of developing BM (64%), probably as a consequence of the prolonged survival due to treatment with EGFR-tyrosine kinase inhibitors (TKIs)." (PMID 29881714, 2018). "After a series of examinations, the patient was diagnosed with lung adenocarcinoma of the left upper lobe (stage IV, cT2N3M1b) harboring L858R mutation in exon 21 of EGFR gene in January, 2015." (PMID 30400855, 2018). "Here, we describe a patient with leptomeningeal carcinomatosis (LM) caused by EGFR-mutated lung adenocarcinoma who was treated with gefitinib via a feeding tube after erlotinib-induced PI." (PMID 30115025, 2018). "Nevertheless, the data imply that in pathological T1 lung adenocarcinoma, EGFR mutations are associated with preoperational serum carcinoembryonic levels ≥ 2.12 ng/mL." (PMID 29849818, 2018). "Testing for EGFR mutations should be considered in not only advanced but also in early stage lung adenocarcinoma patients." (PMID 29435191, 2018). "Multivariate analyses showed that brain metastases at diagnosis and treatment response to afatinib are two important prognostic factors for the overall survival of patients with EGFR mutation-positive lung adenocarcinoma." (PMID 29805772, 2018). "Exon 19 and 21 mutations consist of 90% of EGFR mutation in lung adenocarcinomas, identifying these two kinds of mutations is essential for personalized treatment." (PMID 30547844, 2018). "It is highly plausible that EGFR-mutated advanced lung adenocarcinoma developed in smokers is not only attributed to the oncogenic EGFR mutation but also other smoking-related co-occurring genetic alterations." (PMID 30055587, 2018). "Patients with activating EGFR mutation lung adenocarcinoma receiving first line EGFR TKIs were prospectively enrolled." (PMID 29484139, 2018).
lung adenocarcinoma (continued). "Intriguingly and interestingly, no BRAF mutants were observed among the paired lung adenocarcinomas of BRAF-mutant AAHs; however, in four of the five BRAF-mutant AAHs, the paired lung adenocarcinomas exhibited driver EGFR mutations." (PMID 30060526, 2018). "Owing to genetic advancement, mutations in the epidermal growth factor receptor (EGFR), which play a role in tumour development and progression, have been found in a subset of lung adenocarcinomas and have led to a paradigm shift in therapy." (PMID 29587666, 2018). "In our previous study, brain metastases were found to be a significant prognostic factor for progression-free survival (PFS) in patients with EGFR mutation-positive lung adenocarcinoma receiving afatinib as first-line treatment." (PMID 29805772, 2018). "Our non-randomized, multicenter, phase IV clinical trial including first-line erlotinib treated lung adenocarcinoma patients with activating EGFR mutations was conducted for the very reason." (PMID 29801465, 2018). "All tumours detected were histopathologically parallel to lung adenocarcinoma with identical exon 19 EGFR mutation, excluding a second lung tumour as a possibility." (PMID 30458751, 2018). "Our findings were in line with previous prospective trials that the response rates to EGFR-TKI therapy in stage IV lung adenocarcinoma patients harbouring exon 19 EGFR mutation ranged from 60 to 70%." (PMID 30458751, 2018). "We describe a patient with LM from EGFR-mutated lung adenocarcinoma who was treated with erlotinib followed by gefitinib through a feeding tube for 8 months." (PMID 30115025, 2018). "The EGFR mutation status provides thoracic surgeons with useful information on postoperative follow-up strategies for adenocarcinoma of the lung." (PMID 30290774, 2018). "Both miRNA and mRNA expression profiles were investigated using microarrays in 155 surgically resected specimens of lung adenocarcinoma with a known EGFR mutation status (52 mutated and 103 wild-type cases)." (PMID 30404194, 2018). "Network structural analysis provided a comprehensive view of the complex miRNA–mRNA interactions in EGFR-mutated lung adenocarcinoma, including DUSP4 and MUC4 axes." (PMID 30404194, 2018). "Four hundred and twenty-two patients with EGFR mutation-positive advanced lung adenocarcinoma received gefitinib (n = 195), erlotinib (n = 123), or afatinib (n = 104) as first-line treatment." (PMID 29849936, 2018). "Lung adenocarcinoma with EGFR activating mutations will inevitably acquire resistance to first generation TKIs." (PMID 30103780, 2018). "In another phase III study, 345 patients with stage IIIB/IV lung adenocarcinoma of EGFR mutations (exon 19 deletion, L858R, or other) were randomly assigned to either afatinib (40 mg/day) or cisplatin plus pemetrexed." (PMID 30680072, 2018). "Of 6 somatic DNA changes, 10 epidermal growth factor receptor (EGFR) mutations were detected in eight lung adenocarcinoma samples." (PMID 29769567, 2018). "Here we describe a case of primary EGFR mutation-driven lung adenocarcinoma in a young woman with LFS." (PMID 29854570, 2018). "10–15% of Caucasians and up to 50% of Asians with lung adenocarcinoma have an activating mutation in the EGFR gene, and approximately 93% of adenocarcinomas demonstrate EGFR expression, with 40–80% of adenocarcinomas exhibiting overexpression of EGFR." (PMID 30408128, 2018). "In this study, we sought to build a scoring system to predict Epidermal growth factor receptor (EGFR) exon 19 mutation in lung adenocarcinoma by clinical and radiological features." (PMID 30235778, 2018).
lung adenocarcinoma (continued). "This study is probably one of the largest-scale comprehensive studies about the effect of a first-line EGFR TKI in patients having lung adenocarcinoma harboring uncommon EGFR mutations." (PMID 30428509, 2018). "Somatic mutations in exons encoding the tyrosine kinase domain of the EGFR gene are frequently observed in human lung adenocarcinomas and are associated with sensitivity to some TK inhibitors." (PMID 30060526, 2018). "Next we investigated RPC-9/NaqR cells, which were derived from gefitinib-resistant lung adenocarcinoma cell lines (RPC-9 cells harboring the EGFR exon 19del and T790M mutations)." (PMID 29386539, 2018). "A subset of lung adenocarcinoma with EGFR-tyrosine kinase inhibitor sensitizing mutations (mEGFR) is common in non-smokers and women, suggesting that mutational stressors other than smoking are involved." (PMID 30522449, 2018). "Because both A549 and Panc-1 are KRAS mutant cancer cell lines, we next checked the effects of COPS5 knock-down in H1650 or H2228 lung adenocarcinoma cell lines, which has an EGFR mutation or EML4-ALK fusion, respectively." (PMID 29755680, 2018). "This review presents the current knowledge of the processes of tumorigenesis and progression in early lung adenocarcinoma, with a focus on its clinicopathological characteristics and their associations with driver mutations (EGFR, KRAS, and BRAF)." (PMID 29690599, 2018). "A number of these mRNAs are known to be deregulated in NSCLC, including EGFR-mutated lung adenocarcinoma." (PMID 30404194, 2018). "In a clinical setting of EGFR mutated lung adenocarcinoma, a role of the MDSC apart from T cell suppression was also investigated." (PMID 29484139, 2018). "In the current study, we first identified that the elder was an independent prognostic factor for better PFS in the patients treated with a first-line EGFR TKI for their stage IV lung adenocarcinoma harboring uncommon mutation." (PMID 30428509, 2018). "In this study, patients diagnosed with advanced lung adenocarcinoma harboring susceptible EGFR mutations and treated with EGFR-TKI were grouped based on CSD, and the PFS and OS were compared among the smoking subgroups." (PMID 30055587, 2018). "We identified the oncogenic or biological processes that were characteristically observed in EGFR-mutated lung adenocarcinoma on the basis of miRNA and mRNA expression levels." (PMID 30404194, 2018). "Collectively, these results help define the mechanisms that underlie tumor initiation or progression in EGFR-mutated lung adenocarcinoma." (PMID 30404194, 2018). "Herein, we analyzed the factors affecting the prognosis of patients who received afatinib as a first-line therapy for advanced EGFR mutation-positive lung adenocarcinoma in the real-world setting." (PMID 29805772, 2018). "Epidermal growth factor receptor sensitive mutation was found in 2 MTB-positive patients with lung adenocarcinoma." (PMID 30314434, 2018). "For Asian patients with EGFR-mutant lung adenocarcinoma and brain metastases, erlotinib was associated with a more prolonged PFS and a significantly longer OS compared with gefitinib." (PMID 30458751, 2018). "Epidermal growth factor receptor (EGFR) mutation is prevalently expressed in lung adenocarcinoma cases and acts as one of the major driving oncogenes." (PMID 29321482, 2018). "A 71-year-old woman with epidermal growth factor receptor (EGFR) mutation-positive lung adenocarcinoma was admitted to our hospital because of reduced consciousness." (PMID 30115025, 2018). "In this study, we used miRNA microarray analysis in initial screening of miRNAs which differentially expressed in smoker male patients with stage I lung adenocarcinoma harboring either wild type or mutated EGFR genes." (PMID 29383112, 2017). "In particular, mutations of EGFR (epidermal growth factor receptor) in lung adenocarcinoma have been well studied." (PMID 29137182, 2017).